PGAM1 (phosphoglycerate mutase 1)
Diseases named in the same sentence as PGAM1 in open-access papers (continued):
Sharing a sentence is not in itself a finding about the gene and the disease.
colorectal cancer (7 papers, 2020 to 2024). A primary or metastatic malignant neoplasm that affects the colon or rectum. "M6A-modified circQSOX1 promoted colorectal cancer tumorigenesis by promoting PGAM1 expression by sponging miR-326 and miR-330-5p and further facilitated colorectal immune escape by activating glycolysis and inactivating anti-CTLA-4 therapeutic response." (PMID 38778089, 2024).
non-small cell lung carcinoma (7 papers, 2018 to 2025). A group of at least three distinct histological types of lung cancer, including non-small cell squamous cell carcinoma, adenocarcinoma, and large cell carcinoma. "Conversely, miR-3614-5p was proposed to attenuate proliferation and invasion of non-small cell lung cancer cells by targeting the glycolysis enzyme phosphoglycerate mutase 1 (PGAM1) and the WNT pathway-related NFATC2 transcription factor." (PMID 35935998, 2022). "To elucidate the potential existence of mTOR-PGAM1 cascade in human cancers and its clinical relevance, we examined the relationship of mTOR activity and PGAM1 expression in human non-small cell lung cancer (NSCLC) samples." (PMID 29362480, 2018). "Since human non-small cell lung cancer (NSCLC) was first documented for PEP-based PGAM1 phosphorylation, A549 cell line was chosen as a representative to investigate the significance and mechanism of PKM2–PGAM1 interaction in most experiments of the present study." (PMID 38750259, 2024). "The small molecule HKB99 allosterically blocks PGAM1 and has demonstrated the ability to reduce tumor growth and metastatic potential in a mice model of non-small cell lung cancer by ROS-dependent activation of JNK/c-Jun signaling and abrogation of PGAM1 and ACTA2 interaction." (PMID 38542116, 2024).
ovarian carcinoma (6 papers, 2020 to 2024). A malignant neoplasm originating from the surface ovarian epithelium. "Consistently, PGAM1 was also associated with bevacizumab response in ovarian cancer." (PMID 33446144, 2021). "Our data also demonstrated that NNMT expression was positively correlated with PGAM1 expression in ovarian cancer." (PMID 33446144, 2021). "Based the results of the in vitro experiments above, the effects of circ‐PGAM1 and miR‐542‐3p on biological behaviors of ovarian cancer in vivo were further validated." (PMID 32167655, 2020). "This study further showed that circ‐PGAM1 silencing in ovarian cancer cells increased the expression level of miR‐542‐3p, miR‐542‐3p overexpression in ovarian cancer cells reduced the expression level of circ‐PGAM1." (PMID 32167655, 2020). "Our study confirmed that circ‐PGAM1 promoted proliferation, migration, and invasion and inhibited apoptosis of ovarian cancer cells through down‐regulation of miR‐542‐3p." (PMID 32167655, 2020). "Our preliminary study showed that circ‐PGAM1 (hsa_circ_0019340) is highly expressed in ovarian cancer tissues." (PMID 32167655, 2020). "In summary, our study confirmed that circ‐PGAM1 promoted proliferation, migration, and invasion and inhibited apoptosis of ovarian cancer cells through downregulation of miR‐542‐3p." (PMID 32167655, 2020). "Cell lines (CAOV3 and OVCAR3) overexpressing or silencingcirc‐PGAM1 and miR‐542‐3p were established to explore the functions of circ‐PGAM1 and miR‐542‐3p in ovarian cancer cells." (PMID 32167655, 2020). "Given the important role of PGAM1 in the energy production associated with cell growth and cell proliferations, suggesting that PGAM1 may possibly be serving as a potential biomarker and therapeutic means towards Pt-resistance in ovarian cancer." (PMID 33053689, 2020). "Hence, restoration of PGAM1 can be a contributing factor responsible for apoptosis enhancement so that the level of its expression can be a means for drug resistance in ovarian cancer." (PMID 33053689, 2020). "Dual‐luciferase experiment results further confirmed that miR‐542‐3p is bound to circ‐PGAM1, indicating that circ‐PGAM1 in ovarian cancer cells acted as an miRNA sponge to compete for miR‐542‐3p binding sites through the ceRNA mechanism to regulate miR‐542‐3p activity." (PMID 32167655, 2020). "Next, we further studied whether CDC5L was involved in circ‐PGAM1‐mediated regulation of ovarian cancer cells." (PMID 32167655, 2020). "The mechanism underlying the interaction of circ‐PGAM1/miR‐542‐3p in ovarian cancer has not been reported." (PMID 32167655, 2020). "Furthermore, the circ‐PGAM1/miR‐542‐3p/CDC5L/PEAK1 axis might be a potential therapeutic target in ovarian cancer." (PMID 32167655, 2020). "Therefore, we hypothesized that circ‐PGAM1 might have a tumor‐promotion function similar to that of its parental gene PGAM1 in the development and progression of ovarian cancer." (PMID 32167655, 2020). "PGAM1-mediated glycolytic metabolism plays an important role in paclitaxel resistance, and overexpression of PGAM1 increased glycolytic flux and paclitaxel resistance in SKOV3 paclitaxel-sensitive ovarian cancer cells." (PMID 38434965, 2024). "According to the ceRNA hypothesis, we speculated that circ‐PGAM1 could competitively bind to miR‐542‐3p and attenuate the inhibitory function of miR‐542‐3p on target genes to upregulate target gene expression and further regulate the malignant biological behaviors of ovarian cancer cells." (PMID 32167655, 2020). "The circ‐PGAM1/miR‐542‐3p/CDC5L/PEAK1 pathway played an important role in the progression of ovarian cancer and might be a novel therapeutic target for ovarian cancer." (PMID 32167655, 2020). "Circ‐PGAM1 expression was significantly higher in EOC tissues, and circ‐PGAM1 silencing inhibited proliferation, migration, and invasion and promoted apoptosis of ovarian cancer cells." (PMID 32167655, 2020).
ovarian carcinoma (continued). "This study confirmed that circ‐PGAM1 expression was upregulated in EOC tissues and that circ‐PGAM1 silencing inhibited the proliferation, migration, and invasion and promotes the apoptosis of ovarian cancer cells." (PMID 32167655, 2020). "By increasing miR‐542‐3p expression, circ‐PGAM1 silencing increased its inhibitory effect on CDC5L to decrease CDC5L expression.CDC5L expression was upregulated in EOC tissues, and CDC5L overexpression promoted the malignant biological behaviors of ovarian cancer cells." (PMID 32167655, 2020).
liver cancer (5 papers, 2010 to 2024). An epithelial or non-epithelial malignant neoplasm that arises from the liver. "Several studies have demonstrated that PGAM1 is frequently upregulated in various types of cancers, including lung, breast, colorectal, and liver cancers." (PMID 37338518, 2023). "Collectively, data obtained from diverse experiments demonstrated that suppression of PGAM1 expression resulted in massive liver cancer cell apoptosis." (PMID 20403181, 2010). "PGAM1 knockdown by PGAM1-shRNA-a resulted in remarkable inhibition of liver cancer cell proliferation, which was demonstrated by both MTT and clonogenic formation assays." (PMID 20403181, 2010). "On the other hand, silencing expression of PGAM1 significantly induced liver cancer cell apoptosis both in vitro and in vivo." (PMID 20403181, 2010). "A total of 54 paired liver cancer tissues were collected, and expression of PGAM1 was compared at both transcriptional and translational levels between HCC tissues and the corresponding adjacent noncancerous tissues." (PMID 20403181, 2010). "shRNAs-mediated repression of PGAM1 expression resulted in significant inhibition in liver cancer cell growth both in vitro and in vivo." (PMID 20403181, 2010).
pancreatic ductal adenocarcinoma (5 papers, 2020 to 2024). An infiltrating adenocarcinoma that arises from the epithelial cells of the pancreas. "Other studies also indicated that knockdown of PGAM1 could decrease the proliferative, invasive, and migratory abilities of tumor cells in pancreatic ductal adenocarcinoma and urothelial bladder cancer." (PMID 35674458, 2022). "For instance, PGAM1 promotes pancreatic ductal adenocarcinoma proliferation and metastasis." (PMID 32855383, 2020).
osteosarcoma (4 papers, 2022 to 2023). A usually aggressive malignant bone-forming mesenchymal neoplasm, predominantly affecting adolescents and young adults. "Additionally, the S1P/S1PR3 axis plays a role in promoting cancer cell proliferation and aerobic glycolysis as well as inhibition of apoptosis by activating the YAP/c-MYC/phosphoglycerate mutase 1 axis in osteosarcoma cells." (PMID 35625898, 2022). "S1PR3 signaling promoted aerobic glycolysis by the YAP/c-MYC/PGAM1 axis in osteosarcoma." (PMID 36361531, 2022). "In osteosarcoma, the increased expressions of S1P and its receptor S1PR3 inhibit the phosphorylation of YAP, promote the binding of YAP and cMYC, and finally enhance the transcription of recombinant phosphoglycerate mutase 1 (PGAM1), which is a significant enzyme in aerobic glycolysis." (PMID 37576865, 2023).
schizophrenia (4 papers, 2012 to 2023). A major psychotic disorder characterized by abnormalities in the perception or expression of reality. "Proteomics in the prefrontal cortex and cerebrospinal fluid of patients with schizophrenia have shown altered levels of glycolytic enzymes, including a reduction in PGAM1 expression, which was also observed in a phencyclidine animal model of schizophrenia." (PMID 36768378, 2023). "Although previous studies using postmortem brains of patients with bipolar disorder and schizophrenia suggested altered protein expression of glycolysis enzymes, including PGAM1, the results were controversial." (PMID 23408933, 2013).
colon cancer (3 papers, 2014 to 2024). "Another ATGL-dependent gene in colonospheres is PGAM1, which is involved in glycolysis and is highly expressed in colonic tumors thereby promoting their growth." (PMID 34845203, 2021). "Notably, PGAM1 is highly expressed in many types of tumors, such as liver, lung, breast, and colon cancers and glioblastoma." (PMID 38831394, 2024). "Several glycolysis genes, including glyceraldehyde-3-phosphate dehydrogenase, phosphoglycerate kinase 1 and phosphoglycerate mutase 1, have up-regulation in colon cancer tissues, therefore colon cancer cells have a higher glycolytic rate compared with normal cells." (PMID 24935220, 2014).
COVID-19 (3 papers, 2021 to 2023). A disease caused by infection with severe acute respiratory syndrome coronavirus 2. "In module 4, enhanced glycolysis (increased GAPDH and PGAM1 expression) in patients with mild COVID-19 mediated proinflammatory processes (such as S100 and TNF family) and the IFN-mediated antiviral response in macrophages." (PMID 33936072, 2021). "The CD16+ monocytes in the mild COVID-19 group expressed higher levels of glycolysis-related genes (PGAM1 and GAPDH), a fatty acid-related gene (HACD4), and an arginine and proline metabolism-related gene (SAT2), as well as lower levels of a cysteine and methionine metabolism-related gene (AHCYL1)." (PMID 33936072, 2021). "Consistent with increased glut-1 expression, upregulation of anaerobic glycolytic metabolism involving genes (LDHA, TPi, PGAM1, ALDOA) were identified in severe COVID-19 NKTs." (PMID 37029220, 2023).
glaucoma (3 papers, 2019 to 2021). Increased pressure in the eyeball due to obstruction of the outflow of aqueous humor. "This leads to the hypothesis, that PGAM1 autoimmunity can be triggered by neuroinflammatory conditions also appearing in glaucoma pathogenesis." (PMID 30899261, 2019).
glioblastoma (3 papers, 2010 to 2024). The most malignant astrocytic tumor (WHO grade IV). "We found that protein PGAM1 was highly expressed in both malignant glioblastoma cells as well as tumor-associated monocyte/macrophage cells within the glioblastoma microenvironment." (PMID 38434965, 2024).
lymph node metastasis (3 papers, 2018 to 2024). "In NSCLC, PGAM1 expression is associated with reduced overall and progression-free survival, as well as distant and lymph node metastasis." (PMID 38434965, 2024). "High PGAM1 expression was significantly associated with lymph node metastasis (P = 0.045), distant metastasis (P < 0.001, and clinical stage (P = 0.001)." (PMID 29362480, 2018). "Additionally, elevated PGAM1 expression correlates with clinical features such as tumor grade, lymph node metastasis, and pathological staging, serving as an independent risk factor affecting prognosis." (PMID 38434965, 2024). "Furthermore, univariate and multivariate analysis suggested that PGAM1 expression, lymph node metastasis and TNM stage were independent predictors of OS in patients with NSCLC." (PMID 32855383, 2020). "Moreover, we found that high PGAM1 expression was significantly correlated with advanced TNM stage and lymph node metastasis." (PMID 32855383, 2020).
melanoma (3 papers, 2021 to 2025). A malignant, usually aggressive tumor composed of atypical, neoplastic melanocytes. "In addition to ENO1, PGAM1 is also highly expressed in melanoma tissues." (PMID 35925486, 2022). "We identified phosphoglycerate mutase (PGAM) 2 (Accession No. O70250) and PGAM1 (Accession No. P18669) as novel PA-binding proteins in myoblasts and melanoma cells, respectively." (PMID 41080753, 2025).
pancreatic cancer (3 papers, 2023 to 2024). "Phosphoglycerate mutase 1 (PGAM1) is a glycolytic protein abnormally expressed in cancers that can enhance EMT in pancreatic cancer cells via regulating Wnt/β‐catenin pathway." (PMID 39092293, 2024). "PI3K/Akt/mTOR are found to upregulate the PGAM1 expression in pancreatic cancer cells to induce EMT, contributing to high metastatic potential of pancreatic ductal adenocarcinoma." (PMID 39092293, 2024). "In addition, exosomal PGAM1 could bind to γ-actin (ACTG1), which promotes podosome formation and metastasis in pancreatic cancer." (PMID 38077434, 2023).
bipolar disorder (2 papers, 2013 to 2015). A disorder of the brain that causes unusual shifts in mood, energy, activity levels and the ability to carry out day-to-day tasks. "Of note, our finding of upregulation of just one gene in primary analysis, the PGAM1, in bipolar disorder patients compared with healthy control subjects mirrored previous findings in lymphoblastoid cells." (PMID 26241352, 2015). "The absolute band intensity for the PGAM1 was also significantly higher in patients with bipolar disorder (0.93±0.23 [mean ± standard deviation] [arbitrary unit]) than control subjects (0.39±0.18, p<0.0005)." (PMID 23408933, 2013). "Expression of phosphoglycerate mutase 1 (PGAM1), which is involved in glycolysis, was significantly up-regulated in patients with bipolar disorder (t test, p<0.05)." (PMID 23408933, 2013). "Expression of PGAM1 was recognized by the presence of a single band at around 28 kDa and its protein expression was increased by 197% in bipolar disorder compared with controls (p<0.05)." (PMID 23408933, 2013). "This analysis also showed higher PGAM1 levels in patients with bipolar disorder than controls (p<0.05)." (PMID 23408933, 2013). "The differentially expressed proteins between bipolar disorder and healthy control including PGAM1, might be a clue to understand the biological basis of bipolar disorder." (PMID 23408933, 2013). "An increased level of PGAM1 was observed in samples from patients with bipolar disorder." (PMID 23408933, 2013). "Although PGAM1 cannot be regarded as a qualified biomarker of bipolar disorder from this preliminary finding, it could be one of the candidates for further study to identify biomarkers of bipolar disorder." (PMID 23408933, 2013).
cardiac hypertrophy (2 papers, 2020 to 2023). "Fatty acid oxidation (Acadm, Etfdh, Acadl, Acadvl, Eci1, Hadh, Phyh, Acaa2, Hadha, Hadhb, Cd36), glucose metabolism (Dld, Pdha1, Pgam1, Pgam2, Acss1, Ldhb, Fh1, Slc2a4, Aldh6a1), TCA cycle (Aco2, Dld, Fh1, Ogdh, Sucla2, Sdha, Idh3b, Idh2) were up-regulated by hispidulin in cardiac hypertrophy." (PMID 33324687, 2020).
diabetes (2 papers, 2022 to 2025). "Our results demonstrate a potential role of glycolytic enzymes in beiging of visceral WAT and suggest that PGAM1 would be a novel therapeutic target in obesity and diabetes." (PMID 35521515, 2022).
gastric cancer (2 papers, 2022 to 2025). A primary or metastatic malignant neoplasm involving the stomach. "This pattern was highly reminiscent of that of RB1, indicating that RB1 status might impact PGAM1 status or vice versa in gastric cancers." (PMID 40707487, 2025). "We then investigated whether RB1 controls PGAM1 expression through KDM5A in gastric cancer cells." (PMID 40707487, 2025). "The result showed that 103 genes, including PGAM1, were specifically regulated by the RB1-KDM5A axis in gastric cancer cells." (PMID 40707487, 2025). "Surprisingly, PGAM1 depletion increased sphere formation in gastric cancer cells even without RB1 depletion." (PMID 40707487, 2025). "In contrast, RB1 depletion did not affect histone acetylation in the promoter of PGAM1 of the same gastric cancer cells." (PMID 40707487, 2025). "Indeed, the expression of PGAM1 was downregulated following RB1 depletion in SNU-638 and SNU-601 RB1-positive gastric cancer cell lines however, not in SNU-719 in which RB1 protein has been already inactivated by the product of EBV." (PMID 40707487, 2025).
lung adenocarcinoma (2 papers, 2018 to 2023). A carcinoma that arises from the lung and is characterized by the presence of malignant glandular epithelial cells. "Inversely, the negatively regulated genes by mTOR signaling (gene set: MTOR_UP.N4.V1_DN, right) were enriched in the PGAM1-low expression groups, in both lung adenocarcinoma (ADC) and lung squamous cell carcinoma (SCC) subtypes of NSCLC." (PMID 29362480, 2018). "We found that high expression levels of PGAM1 and PGAM4 in lung adenocarcinoma (LUAD) patients and NOL6 in lung squamous cell carcinoma (LUSC) patients were associated with low overall survival rates." (PMID 37667226, 2023).
multiple sclerosis (2 papers, 2019 to 2024). A progressive autoimmune disorder affecting the central nervous system resulting in demyelination. "Autoantibodies to PGAM1 have been found increased in multiple sclerosis and neuromyelitis optica and have been suggested as marker for neuroinflammatory diseases." (PMID 30899261, 2019). "PGAM1 is an enzyme of glycolysis, and serum autoantibodies against PGAM1 have been reported in autoimmune hepatitis and various neurological diseases, including multiple sclerosis and neuromyelitis optica." (PMID 38652420, 2024).
osteoarthritis (2 papers, 2018 to 2023). A noninflammatory degenerative joint disease occurring chiefly in older persons, characterized by degeneration of the articular cartilage, hypertrophy of bone at the margins and changes in the synovial membrane. "Our laboratory previously published an autoantibody panel which consisted of Annexin 1, Annexin 2, IMPDH2, HSP70, PGAM1, and Ubiquillin 1, and properly classified 93% within five clinically distinct groups: osteoarthritis, “cancer-free” control, asthma/COPD, benign nodule, and NSCLC." (PMID 37190187, 2023).